RN7SKP281 (RN7SK pseudogene 281)
Gene: Miscellaneous RNA gene on chromosome 2 (157,298,807 to 157,299,158, reverse strand). Ensembl gene ENSG00000222404.
Homologues: Orthologues: chimpanzee 7SK (99% identical). Paralogues in human: RN7SKP255 (69% identical), RN7SKP203 (68% identical), 7SK (67% identical), RN7SKP176 (67% identical), RN7SKP180 (67% identical), RN7SKP71 (66% identical), RN7SKP124 (66% identical), RN7SKP9 (65% identical), RN7SKP33 (64% identical), RN7SKP37 (64% identical), RN7SKP79 (64% identical), RN7SKP146 (64% identical), and 283 more.